INS (insulin)
Diseases named in the same sentence as INS in open-access papers (continued):
Sharing a sentence is not in itself a finding about the gene and the disease.
Insulin resistance (continued). "In addition, knockout of TNF-α or its receptor significantly enhanced insulin sensitivity and pharmacological inhibition of TNF-α attenuated obesity-induced insulin resistance." (PMID 35807921, 2022). "The mechanism of leptin contribution to the development of insulin resistance may lie in its capacity to phosphorylate insulin receptor 1 substrate (IRS1) serine residues, which downregulates insulin signaling." (PMID 35682958, 2022). "To further investigate whether Cori treatment has an improvement effect on glucose intolerance and insulin resistance during the progressive development of NAFLD, we performed glucose tolerance test (GTT) and insulin tolerance test (ITT) assays." (PMID 36071929, 2022). "Using the homeostatic assessment of insulin resistance (HOMA-IR), HOMA2IR, the quantitative insulin-sensitivity check index (QUICKI), fasting serum insulin, and FPG/FSI to measure IR, we showed that BMI adjusted for age and sex performs similarly to many of the newer indices in our sample." (PMID 36275055, 2022). "Insulin-stimulated GLUT4 dispersal is impaired in a model of insulin resistance, suggesting that this dispersal could play a role in the development of insulin resistance." (PMID 36446811, 2022). "The Nutrition to Optimize, Understand, and Restore Insulin Sensitivity in HIV for Oklahoma (NOURISH-OK) study will result in an integrated, multi-level understanding of how food insecurity contributes to insulin resistance, which is central to the pathogenesis of many chronic co-morbidities in HIV." (PMID 36225538, 2022). "Moreover, glucose and insulin tolerance tests (GTT and ITT) showed that curcumin improved HFD-induced glucose intolerance and insulin resistance, respectively." (PMID 36348361, 2022). "Under conditions of selective insulin resistance, insulin fails to suppress hepatic glucose production, while augmenting hepatic lipogenesis and TG accumulation." (PMID 35349482, 2022). "In addition, the degree of IR can be indexed by the homeostasis model assessment of insulin resistance (HOMA-IR) according to the homeostasis model assessment, which is calculated with the use of fasting glucose and insulin levels." (PMID 36498726, 2022). "Regarding glucose metabolism, PTX has been suggested to improve insulin resistance with a decrease in the Homoeostasis Model Assessment of Insulin Resistance (HOMA-IR), which is a proxy of insulin resistance taking into account fasting blood glucose and insulin." (PMID 35268464, 2022). "Unfortunately, we did not assess insulin resistance in this study, but it has been reported that patients with SO are in an insulin-resistant state." (PMID 35438441, 2022). "We argue that in an insulin resistant state, such as in DMCM, LF diets may worsen glycaemic control and promote further insulin resistance (IR), contributing to a physiological and functional decline in DMCM." (PMID 35529461, 2022). "Compared to the cognitive–behavioral intervention, the mindfulness-based group intervention showed significant reductions in fasting insulin levels and insulin resistance 6 weeks after the intervention but not at the follow-up assessment after 6 months." (PMID 35682203, 2022). "Type-2 diabetes mellitus (T2DM) is a condition characterized by high blood glucose level, insulin resistance, and lack of insulin secretion." (PMID 35909524, 2022). "Thus, the protein expression of the insulin pathway inhibitors TXNIP and ARRDC4 decreased and improved insulin resistance and lipotoxicity." (PMID 36059548, 2022). "Insulin resistance is a phrase used to characterize the illness known as type 2 diabetes, which is independent of insulin." (PMID 36060389, 2022). "Insulin resistance generally refers to a state where the tissues do not respond sufficiently to physiological concentrations of insulin." (PMID 36358481, 2022).
Insulin resistance (continued). "Therefore, it is well established that impaired skeletal muscle MBF is a contributor to insulin resistance, and improvements in MBF can augment insulin sensitivity." (PMID 35676248, 2022). "In the most common form of DM, known as insulin-independent type 2 DM, or T2DM, the body fails to incorporate insulin properly, which ultimately results in insulin resistance." (PMID 35056163, 2022). "These supplements significantly reduced insulin resistance (FBS levels, serum insulin levels (INS), insulin resistance (HOMA‐IR) and HOMA‐B measures), lipid profile (serum cholesterol, VLDL‐cholesterol concentrations, and total cholesterol/HDL levels), inflammation markers (TNF, and IL‐6)." (PMID 35243684, 2022). "In another randomized cross-over sleep extension study of 21 short-sleeping non-diabetic working-age adults, those who extended their sleep to >6 h/night for 2 weeks had significant improvement in fasting insulin resistance (HOMA-IR), early insulin response to glucose, and β-cell function." (PMID 35659776, 2022). "We did not study the insulin resistance phenotype in more detail as high glucose or insulin levels occurred later as a secondary consequence of obesity." (PMID 35425699, 2022). "Lack of insulin or systemic and cardiac insulin resistance induces a decrease in glucose transport and a compensatory increase in insulin production, resulting in hyperinsulinemia and impaired insulin metabolic signaling." (PMID 36552599, 2022). "However, the most outstanding performance was that of insulin infusion (CSII) combined with metformin, which had the best clinical effect in controlling blood sugar and improving insulin resistance." (PMID 36015100, 2022). "Adipo-IR, homeostasis model assessment-estimated insulin resistance (HOMA-IR), homeostasis model assessment of β-cell function (HOMA-B), quantitative insulin sensitivity check index (QUICKI), and single point insulin sensitivity estimator (SPISE) indices were calculated." (PMID 36004027, 2022). "On the contrary, SGLT2 inhibitors did not lower insulin resistance or improve insulin secretion, which are the major pathological defects in type 2 DM." (PMID 35806147, 2022). "Another more important reason was that the indexes like HOMA-IR and HOMA-β and fasting insulin levels were not adequate to reflect the insulin resistance or β-cell function." (PMID 35634496, 2022). "According to the more accepted model performed in obese subjects of European descent, under conditions of obesity-related insulin resistance, β-cells are stimulated to secrete more insulin than in normal insulin sensitivity." (PMID 36614099, 2022). "Furthermore, treatment with ANP in human cultured adipocytes reduced insulin-induced PCSK9 expression, especially in the context of hyperglycemia, simulating a clinical condition of insulin resistance/T2DM in our recent experimental study." (PMID 36009507, 2022). "In patients without a DM history, homeostasis model assessment of insulin resistance (P = 0.017), insulin sensitivity index (P = 0.019) and C-peptide sensitivity index (P = 0.020) were statistic associated with T staging." (PMID 35299970, 2022). "The complex pathogenesis of type 2 diabetes is not very clear but it is widely accepted that insulin resistance and impaired insulin secretion are the major hallmarks of type 2 diabetes." (PMID 36079819, 2022). "The insulin signaling defect is an important clinical marker (insulin resistance) of PCOS, which is independent of obesity." (PMID 35327342, 2022). "Clinically, non-specific indicators of insulin resistance, such as basal glucose and insulin concentrations, glucose tolerance tests, and proxy measurements, can be performed." (PMID 35030228, 2022). "It does not appear that changes in glucose or insulin levels nor changes in insulin sensitivity or insulin resistance influenced the expression of miRNA levels in the third trimester, except for miR-134-5p." (PMID 35203692, 2022).
Insulin resistance (continued). "Obesity, hyperglycemia, peripheral insulin resistance, and cytokine levels are the main features of type 2 diabetes (T2D), a complicated metabolic condition that results in a relative lack of insulin and β-cell failure." (PMID 36430158, 2022). "In addition, prenatal fatty liver must provoke severe insulin resistance in the offspring of HFD-fed dams beginning early in life, accompanying the inhibition of insulin-stimulated glucose uptake." (PMID 35907977, 2022). "As insulin resistance was evaluated with HOMA-IR, the β-cell dysfunction is evaluated with HOMA-BETA (β).Increasing glucose concentrations in the arteries induce the pancreatic β-cells to secrete insulin." (PMID 37654824, 2022). "In some NAFLD patients with insulin resistance, insulin fails to restrain hepatic glucose production, whereas increased hepatic lipogenesis is sustained, namely selective insulin resistance, exacerbating both the hyperglycaemic and hyperlipidaemic situations." (PMID 35713152, 2022). "In HFD fed mice, FGF21 increases insulin-stimulated AKT phosphorylation and glucose uptake in the skeletal muscle, while in human skeletal muscle myotubes, FGF21 prevents palmitate-induced insulin resistance." (PMID 35409319, 2022). "The timeline for chronic hyper-secretion of insulin, either during fasting or after a meal, to trigger “insulin resistance” is not precisely known." (PMID 36278750, 2022). "This demonstrates that insulin acutely represses lipogenesis and proposes that insulin resistance is inclusive of a defective insulin signaling against de novo lipogenesis as well as gluconeogenesis." (PMID 36009446, 2022). "Diabetic cats are, on average, six times less sensitive to insulin than normal cats, but hepatic gluconeogenesis is also increased in non-diabetic cats with insulin resistance." (PMID 35968003, 2022). "β-arrestin 1 can alter insulin signaling by inhibiting insulin-induced proteasomal degradation of IRS-1 and the inhibition of beta-arrestin-1 leads to enhanced IRS-1 degradation and accentuated cellular insulin resistance." (PMID 35430346, 2022). "Furthermore, fasting serum glucose, insulin, and HOMA-IR index in insulin-resistant mice decreased after BBR treatment." (PMID 36105164, 2022). "Among the surrogate endpoints, AX consumption reduced homeostatic model assessment of insulin resistance (HOMA-IR; insulin resistance index; p = 0.006) and increased quantitative insulin sensitivity check index (QUICKI; insulin sensitivity index, p = 0.008) compared to the MCC group." (PMID 35562794, 2022). "Low carbohydrate diets proved to be more effective than higher carbohydrate (low fat) diets in improving fasting glucose and insulin and insulin sensitivity as measured by HOMA-IR in individuals with obesity and insulin resistance and patients with obesity and non-alcoholic fatty liver disease." (PMID 35677551, 2022). "DM can be classified into two major types: type I DM (insulin-dependent) due to immune-mediated β cells destructions; and type II DM (non-insulin-dependent) due to an insulin secretory defect and insulin resistance." (PMID 35057448, 2022). "Insulin resistance with hyperglycemia and defective insulin signaling results in neurons lacking energy and becoming vulnerable to oxidative damage and apoptosis, accelerates cognitive decline." (PMID 36364766, 2022). "Second, due to the limitation of data, other insulin resistance indicators such as HOMA-IR or serum insulin levels were not measured and compared to the TyG index." (PMID 36362646, 2022). "In these models, impairment of insulin/IGF-1 signaling did not necessarily lead to systemic insulin resistance." (PMID 36198696, 2022). "On the other side, klotho might induce insulin resistance in adipocytes, preventing insulin effects on promotion of GLUT4 plasma membrane translocation, and attenuating intracellular insulin signalling through main mediators, such as Akt, GSK3β, and PFKf3β." (PMID 35279809, 2022).
Insulin resistance (continued). "In general, fasting plasma insulin levels should not be higher than 15 uIU/ml, and fasting hyperinsulinemia in people with normal blood glucose is considered a marker of insulin resistance." (PMID 35299970, 2022). "Taken together, insulin resistance may not directly cause AD; however, insulin resistance can increase the risk of developing AD by exacerbating AD pathology (e.g., Aβ, tau and chronic neuroinflammation) and, in turn, promote further insulin resistance—a feed‐forward loop." (PMID 35128745, 2022). "Supplementation with TetraSOD® resulted in no significant changes in insulin levels or insulin resistance and sensitivity, as measured by the HOMA-IR and R-QUICKI indices, respectively, in CAF-fed rats compared to those supplemented with the vehicle." (PMID 36235679, 2022). "As a result, glucose uptake from the bloodstream increases, thereby reducing blood glucose levels and insulin resistance by not requiring as much insulin." (PMID 36360995, 2022). "We suggest that permanent AMPKα activation through statins and the blocking of its insulin-dependent counterpart AKT may lead to metabolic inflexibility and insulin resistance in the long run." (PMID 35216514, 2022). "The current understanding of T2DM development is that increased insulin resistance is a key pathologic step in early stages when the β-cell dysfunction is not yet preponderant and the insulin overproduction can still cope with the higher demand." (PMID 35897035, 2022). "Nevertheless, the GSH levels, which in this study are attributed insignificantly to the insulin resistance due to the dose–response effect of the time exposure of insulin, are not sufficient." (PMID 35955446, 2022). "It is not surprising that impaired insulin secretion and insulin resistance or their combination are important subgroups of T2D." (PMID 35956377, 2022). "The higher levels of insulin were consistent with the increased HOMA-IR in the T2DM animals (3.58 ± 0.36) as compared to the control animals, which showed (0.67 ± 0.07), thus corroborating that the T2DM animals developed insulin resistance (SP = 100%)." (PMID 36012191, 2022). "For example, immune cell-derived proinflammatory cytokines such as TNF block insulin signaling by inactivating insulin receptor substrate (IRS), leading to insulin resistance and exacerbating blood glucose levels due to the downregulation of glucose transporters on adipocytes." (PMID 34837070, 2022). "We confirm previous studies showing reduced dispersal in a model of insulin resistance, and further show that both insulin-stimulated GLUT4 delivery to the plasma membrane and insulin-stimulated GLUT4 dispersal are negatively correlated with cell size in adipocytes." (PMID 36446811, 2022). "Our results demonstrate that MKP-2 is a major regulator of p38 MAPK, JNK, and ERK activities in insulin responsive tissues, and upregulation of MKP-2 in obesity contributes to the development of insulin resistance, fatty liver disease, and metabolic dysfunction." (PMID 35745205, 2022). "While the effect on insulin secretion was expected, no previous studies reported an improvement in insulin resistance during PAS therapy." (PMID 35563608, 2022). "When cells do not properly utilise insulin in the beginning, this condition is known as insulin resistance." (PMID 36060389, 2022). "The previous studies indicated that metformin and bromocriptine might alleviate hepatic insulin resistance through modulating the STAT3-dependent pathway, insulin sensitivity, and gluconeogenesis." (PMID 35956419, 2022). "Unfortunately, we did not evaluate insulin resistance by plasma insulin, HOMA‐R, and other indicators." (PMID 34236141, 2021). "Fasting glucose, insulin and HOMA-IR were measured to assess insulin resistance." (PMID 34208400, 2021).
Insulin resistance (continued). "GMP hydrolysate (GHP) has been found to increase the level of hepatic glycogen and ameliorate hepatic insulin resistance in high-fat diet (HFD)-fed mice, suggesting that GHP may improve the insulin sensitivity of insulin target organs." (PMID 34071375, 2021). "Insulin resistance or lack of insulin secretion can affect neuron survival, which later contributes to neurodegenerative diseases." (PMID 33672590, 2021). "In particular, insulin in the olfactory bulb affects smelling capacity, adiposity, and insulin resistance with a strong negative mediating effect of insulin resistance on olfactory sensitivity to food odors." (PMID 34945673, 2021). "Regarding metabolic parameters, participants with sexual dysfunction had higher glucose levels, insulin levels, and insulin resistance compared with those not experiencing sexual dysfunction." (PMID 34421613, 2021). "In addition, theelevated fasting plasma insulin and insulin resistance were reversed by melatoninsupplementation, which might be due to increase in insulin sensitivity as earlierreported by McHugh and Cheng that administration of melatonin improves insulinsensitivity and insulin level." (PMID 34879109, 2021). "As above for the REFLECT studies, no fasting insulin or glucose values were recorded, so it was not possible to assess interaction between changes in insulin level or insulin resistance and cognition or these pharmacodynamics markers." (PMID 34220427, 2021). "An opposite effect of insulin resistance can be observed in muscles, where a lack of insulin signal leads to a significant reduction of its metabolic rate and induction of autophagy." (PMID 33659253, 2021). "The other opinion is that increased insulin secretion is primary hypersecretion independent of compensatory response to insulin resistance." (PMID 34867781, 2021). "The results showed that MBBP‐bread could effectively decreased serum insulin content of T2DM mice, and can improve insulin resistance to a certain extent." (PMID 34026064, 2021). "The paradoxical normal insulin sensitivity, found in the OLD mice, led us to ask whether age-insulin resistance is an obligatory finding." (PMID 34054736, 2021). "MCK-PGC-1α mice have also been reported to be even more prone to fat-induced insulin resistance due to decreased insulin sensitivity in muscle rather than providing protection against insulin resistance." (PMID 33200398, 2021). "An important feature of metabolic syndrome is insulin resistance, characterized in nondiabetics by increased levels of serum insulin, and it has been suggested that insulin itself is atherogenic." (PMID 34442386, 2021). "Paradoxical to the results indicating exaggerated insulin resistance in the ED group, in sfED and SD mice, there were no distinct changes observed in the serum insulin concentrations." (PMID 33917297, 2021). "Atg7 deletion in SF1 neurons only implied moderate changes in fed plasma insulin levels and insulin resistance, without changes in glycemia and glucose tolerance." (PMID 34201257, 2021). "In the present study, EA improved blood glucose by reducing insulin resistance rather than by increasing insulin secretion." (PMID 34221088, 2021). "Over time, the lack of insulin production eventually leads to an inability to correct insulin resistance, which inadvertently gives rise to hyperglycaemia and T2DM." (PMID 33557218, 2021). "In the case of our results, we did not see a clear effect of obesity on glucose metabolism or insulin signalling, reinforcing that skeletal muscle insulin resistance in women with PCOS is not a result of an intrinsic defect." (PMID 34707569, 2021). "To explore these mechanisms, we related global skeletal muscle gene expression profiling of 38 non-diabetic men to a surrogate measure of insulin sensitivity, i.e. homeostatic model assessment of insulin resistance (HOMA-IR)." (PMID 33639916, 2021).